IL6 (interleukin 6)
Diseases named in the same sentence as IL6 in open-access papers (continued):
Sharing a sentence is not in itself a finding about the gene and the disease.
colitis (continued). "To specifically assess whether Th17 cell differentiation inducing and/or Th17 cell promoting cytokines are differentially regulated, we compared colonic gene expression profiles of IL-12 (Th1) and IL-1ß/IL-6/IL-23 (Th17) between colitis-protected Rag1−/−Irf4−/− and colitic IRF4-competent mice." (PMID 33584655, 2020). "In berberine‐administrated mice with colitis, levels of such pro‐inflammatory cytokines in the colon and sera were significantly decreased, which was accompanied by a reduction in colonic macrophages and percentages of IL‐6+, IL‐1β+ and TNF‐α+ secreting macrophages among splenocytes." (PMID 33135395, 2020). "Similarly, IL-6 is also a therapeutic target in the clinical management of colitis." (PMID 31010141, 2019). "Treatment with UroA/UAS03 significantly protected from DSS-induced colitis as evident from decreased gut permeability, reduced shortening of colons, increased colon weight/length ratio, reduced inflammation (serum IL-6, IL-1β, TNF-α as well as colonic tissue MPO levels)." (PMID 30626868, 2019). "In accord with previous work, such blockade of IL-10 signaling resulted in typical features of colitis, including loss of weight/adiposity, splenomegaly, colomegaly, colon shortening, elevated MPO, increase in pathohistological scoring, and elevations in serum IL-6 and CXCL1." (PMID 31827095, 2019). "However, Paneth cell metaplasia can be found in various types of colitis, in which case this mechanism of IL-6-facilitated epithelial repair could play a role." (PMID 29922293, 2018). "However, IL-6 is a pleiotropic cytokine and under certain conditions, IL-6 may augment established Th1 responses, including Th1 mediated colitis and Th1 and Th17 immune reactivity in experimental autoimmune encephalitis." (PMID 29410442, 2018). "In addition, the administration of apelin to Il10−/− mice with established colitis resulted not only in an amelioration of disease by lowering the production of pro-inflammatory cytokines such as TNFα, IL-6, and IL-1β but furthermore enhanced intestinal lymphatic function." (PMID 30369924, 2018). "The data show that oral administration of MORE and MOHRE can significantly decrease the serum levels of TNF-α, IL-6, and IL-17 in colitis mice, suggesting that MORE and MOHRE could suppress the production of proinflammatory cytokines and then relieve the inflammatory response." (PMID 28824631, 2017). "Thus, we hypothesize that targeting IL-6 by ONX 0914, as the main contributor to colitis-associated as well as sporadic CRC, might reduce intestinal inflammation and therefore reduce the subsequent risk for colon cancer formation." (PMID 28881611, 2017). "As colon biopsies and sera from IBD patients have increased concentrations of TNF-α and IL-6, the suppressive effect of GpS on TNF-α and IL-6 production in the colons of colitis mice may also indicate the potential inhibitory effect of GpS on NF-κB and STAT3 signaling." (PMID 29152090, 2017). "Luminal ATP triggers Th17-prone molecules, such as IL-6, IL-23p19 and TGFβ-activating integrin-αV and -β8 from a CD70high CD11clow subset of the lamina propria cells, and administration of ATP exacerbates a T-cell-mediated colitis model with enhanced Th17 differentiation." (PMID 28670480, 2017). "Taken together, our data suggest that administration of SHH inhibitors could be an effective strategy to prevent colitis-induced colorectal carcinogenesis, mainly by targeting IL-6 signaling, ablating CSCs, and suppressing oncogenic inflammation, achieving chemoquiescence ultimately." (PMID 26716648, 2016). "Moreover, the IL-6/STAT3 pathway is an important target in DSS induced colitis therapy." (PMID 27258062, 2016). "Plasma levels of IL-1β, IL-6, IL-10, IL-17, TNFα, and IFNγ were detected in blood samples from all experimental mice group at two different time points, one corresponding to the acute phase of colitis (day 25), and one at the end of the recovery phase (day 37)." (PMID 26973525, 2016).
colitis (continued). "Furthermore, HBO2 treatment alone did not change the expression of proinflammatory cytokines in the colon, MLN, or spleen of the control mice; however, DSS-induced colitis resulted in a significant IL-1β and IL-6 gene upregulation in the colonic tissue and IL-2 gene upregulation in the MLN." (PMID 27656047, 2016). "Interestingly, Nfkbid−/− mice show a high sensitivity to lipopolysaccharide (LPS)-induced endotoxin shock and 4,4-dimethyl-4-silapentane-1-sulfonic acid-induced colitis because Nfkbid−/− DCs and macrophages produce large amounts of IL-6 in response to LPS stimulation." (PMID 25347393, 2014). "It was also reported on experimental model of colitis-associated colorectal carcinoma, that NFATC2-deficient mice were protected from tumor development and show significantly reduced levels of the downstream critical proinflammatory cytokines interleukin IL21 and IL6." (PMID 24416320, 2014). "Moreover, it has been documented that IL-6 exhibits two contrasting features; it acts as a proinflammatory cytokine in models of chronic inflammatory diseases, that is, collagen-induced arthritis, murine colitis, or experimental autoimmune encephalomyelitis." (PMID 24715817, 2014). "Furthermore, TNFα was able to inhibit the up-regulation of hepcidin induced by IL-6 in the Huh7 cells, which could help to explain why hepcidin expression was decreased during DSS colitis despite increased levels of IL-6 produced by the colon." (PMID 22675442, 2012). "Notably, mice lacking IL-6 (IL-6 null) or STAT3 in IECs show reduced CAC tumorigenesis but develop more severe DSS-induced colitis, with pronounced colonic ulceration and body weight loss, than do wild-type counterparts." (PMID 22962574, 2012). "However, serum levels of IFN-γ, IL-1α, IL-6, and IL-17 were elevated at baseline in the serum of T/I mice (these mice had colitis at the time of assessment) compared with WT mice and IFN-γ and IL-17 did not significantly increase in the serum of T/I mice following challenge with LPS." (PMID 22848611, 2012). "Recent circumstantial evidence has further strengthened the idea that the IL-6/gp130/STAT-3 signaling axis serves as both an autocrine and paracrine amplification loop in lung adenocarcinoma, multiple myeloma, Ras-transformed cancer cells, and a colitis-associated cancer model." (PMID 22022583, 2011). "The proliferative and survival effects of IL-6 on IEC are largely mediated by the transcription factor Stat3 as mice lacking Stat3 in colonic epithelium develop fewer adenomas in spite of the fact that they have more severe colitis following exposure to AOM-DSS." (PMID 20885960, 2010). "Numerous studies have reported elevated IL-6 levels in several inflammatory diseases, including chronic inflammatory and fibro-proliferative diseases such as keloids, rheumatoid arthritis, inflammatory bowel disease (colitis), multiple sclerosis, and pulmonary fibrosis." (PMID 19907660, 2009). "With regard to IL-6, a broad spectrum cytokine with characteristics of an acute-phase reactant, mucosal cytokine levels are elevated consistently in IBD tissues and neutralization of soluble IL-6 receptors in vivo causes suppression of colitis activity and induction of apoptosis." (PMID 18612433, 2008). "Serum analysis showed that EGT significantly lowered DSS-elevated levels of IL-6, IL-1β and TNF-α, confirming its systemic anti-inflammatory effects in this colitis model." (PMID 41530565, 2026). "Studies in murine DSS-induced colitis models show that CST treatment significantly reduced colonic levels of pro-inflammatory cytokines such as IL-1β, IL-6, IL-18, and TNF." (PMID 40370467, 2025). "RT-PCR analysis revealed that the expression levels of three genes, including IL-6, TNF-α, and TGF-β, in the colon tissue of the colitis group were higher than those of the control group." (PMID 40896701, 2025).
colitis (continued). "In the current study, AVCP administration significantly reduced the elevated serum levels of IL-1β, IL-6, TNF-α, and IL-17A induced by DSS in mice, which suggests that AVCP can reduce inflammation in colitis mice." (PMID 40507195, 2025). "The study found that CW notably reduced the mRNA levels of pro‐inflammatory markers including TNF‐α, IL‐1β, IL‐6, Toll‐like receptor 4 (TLR4), and iNOS, while it enhanced the expression of the anti‐inflammatory cytokine IL‐10 in colitis." (PMID 39830908, 2025). "In colitis, TH reduces colitis biomarkers such as MPO and pro-inflammatory cytokine IL-6, thereby mitigating inflammation." (PMID 40298838, 2025). "In response to DSS-induced colitis, pro-inflammatory cytokine levels (TNF-α, IL-1β, IL-6, IFN-γ, NF-κB, IL-17, and TGF-β) were significantly elevated in group 2, indicating their role in the pathogenesis of UC." (PMID 40502390, 2025). "Recent studies have explored colitis-induced lung inflammation in DSS mice models, focusing on molecular pathways such as inflammasome activation and IL-6 signalling." (PMID 40435188, 2025). "By stopping the production of TNF-α, IL-6, and IL-1β in animals with DSS-induced colitis, AVE was shown to have anti-inflammatory effects in this study." (PMID 40699788, 2025). "Treatment with mesalamine resulted in a modest but significant reduction in IL‐6 and STAT3 content by 12.71% (F = 505.4, p = 0.006) and 53.57% (F = 153.3, p = 0.004), respectively, relative to the colitis group." (PMID 40387460, 2025). "Our results showed that prefeeding with B. velezensis MZ09 reduces the levels of the proinflammatory cytokines IL-6 and TNF-α in a DSS-induced colitis model, thus alleviating colonic damage." (PMID 40883849, 2025). "A bifunctional PGH named LPH, derived from lactobacilli, attenuated TNBS-induced colitis in mice by digesting PGN and releasing NOD2 ligands, thereby increasing IL-10 and decreasing TNF-α, IFN-γ, and IL-6, exerting an anti-inflammatory activity." (PMID 41301527, 2025). "Blocking the NAD+ salvage pathway inhibited the secretion of IL‐1β, IL‐6, IL‐8, IL‐18, and TNF‐α in the serum and reduced the expression of TNF‐α in the tissues of F. nucleatum‐infected IFX‐treated DSS‐induced colitis mice." (PMID 39739648, 2025). "It is well known that pro-inflammatory factors such as TNF-α, IL-1β, IL-6, and IFN-γ play important roles in colitis progression." (PMID 40529132, 2025). "Under the anti-inflammatory properties, in the TNBS-induced colitis model, placenta tissue-derived MSC-EVs significantly reduced levels of IL-6 and TNF-α, contributing to the amelioration of disease severity and improved histological architecture." (PMID 41551594, 2025). "We then measured the expression of colitis-aggravating factor, SERPINE1/PAI-1, and endogenous IL-6 levels in Caco-2 cells." (PMID 40297589, 2025). "ANP secreting strain can effectively alleviate dextran sulfate sodium (DSS) induced colitis in mice, which are manifested as downregulation of TNF-α, interleukin-1β (IL-1β) and upregulation of interleukin-6 (IL-6) in colon tissues." (PMID 41415685, 2025). "It has been shown that MOS promotes macrophage polarization to the M2 type by targeting the SIGNR1 receptor in a DSS-induced murine colitis model, which in turn down-regulates the expression of pro-inflammatory factors such as TNF-α and IL-6." (PMID 40732026, 2025). "paracasei L9 can enhance the abundance of butyrate-producing bacteria, thereby inhibiting the IL-6/STAT3 signaling pathway and alleviating the development of DSS-induced colitis." (PMID 41515240, 2025). "Our previous study demonstrated a significant elevation of IL-6, TNF-α, IL-1β, IL-17, IFN-γ and MCP-1 in colitis and showed that activation of the CB2 receptor by HU308 significantly reduces these cytokine levels." (PMID 40005963, 2025).
colitis (continued). "Mechanistically, L. curvatus DCF0620 treatment controlled the infiltration of cells that express pro-inflammatory cytokines (TNF-α, IL-1β, IL-6, and IL-17) and fibrotic markers (TGF-β, Col1, and α-SMA) into the intestinal tissue of DSS-induced colitis mice." (PMID 41567191, 2025). "Our observations indicated that muscone downregulated the expression levels of proinflammatory cytokines, including IL-1β, IL-6, TNF-α, IL-17, and IL-33, in DSS-induced colitis." (PMID 40452925, 2025). "In a severe colitis rat model, AMSC transplantation improved colitis by inhibiting monocyte/macrophage activity, lowering inflammatory markers (TNF-α, IL-6, and IL-1β), and preventing NF-κB activation." (PMID 40076934, 2025). "paracasei L9 expressing Amuc_1100 protein, mRNA levels of pro-inflammatory cytokines (IL-6, TNF-α, and IL-1β) and anti-inflammatory cytokines (IL-4 and IL-10) were measured in colon tissues of DSS-induced colitis mice." (PMID 41515240, 2025). "Muscadine wine polyphenols were shown to prevent weight loss and colon shortening, downregulate the NF-κB pathway and secretion of IL-1β, IL-6, and TNF-α in the colon of mice with DSS-induced colitis." (PMID 40732952, 2025). "In the context of active colitis, its upregulation likely represents the host’s attempt to counterbalance the overwhelming production of pro-inflammatory cytokines (e.g., TNF-α, IL-6) and to restrain overactive immune cells." (PMID 41517138, 2025). "DSS-induced colitis is characterized by elevated MPO activity, pro-inflammatory cytokines (TNF-α, IL-6, IL-1β), and lipid peroxidation, alongside depleted antioxidant defenses (SOD, CAT, GSH)." (PMID 41395463, 2025). "Wedelolactone markedly reduced the IL-1β-induced expression of COX-2, iNOS, TNF-α, and IL-6 in human chondrocytes by inhibiting NF-κB activation and further attenuated colonic inflammation in DSS-induced colitis via suppression of the IL-6/STAT3 axis." (PMID 41304898, 2025). "DNA from the VSL#3 probiotic formulation induced IL-6 and IL-12p40 secretion in bone marrow-derived macrophages (BMDMs) by activating NF-κB and JNK pathways and protected mice against DSS-induced colitis through a TLR9-MyD88-dependent mechanism." (PMID 41301527, 2025). "Biochemical analysis showed that GPE downregulated the levels of the pro-inflammatory cytokines interleukin-1 (IL-1), IL-6, IL-17, tumor necrosis factor-alpha (TNF-α), and nuclear factor-kappa B (NF-κB), compared to the colitis (AA) group." (PMID 40732258, 2025). "However, the lack of Mcpt-4 could induce significant increase of TNF-α and IL-6 in colitis mice." (PMID 40697820, 2025). "In the present study, colonic levels of IL‐6 and STAT3 were significantly decreased in the PTX‐treated, mesalamine‐treated, and combination‐treated groups compared to the colitis group." (PMID 40387460, 2025). "Our co-culture system consisting of THP-1 macrophages and Caco-2 intestinal cells revealed that the dual inhibition of MCT4 in both cell types reduced colitis-related inflammatory markers such as SERPINE1/PAI-1 and IL-6 in intestinal cells." (PMID 40297589, 2025). "In a murine model of acetic acid-induced colitis, pregabalin reduced both macroscopic and microscopic intestinal damage and inflammation, decreasing colonic levels of TNF-α, IL-6, IL-1β, and myeloperoxidase (MPO) activity [DOI: 10.4103/1735-5362.329924]." (PMID 40650291, 2025). "UV‐C inactivated Lacticaseibacillus casei 39 paraprobiotic suppressed inflammation (↓TNF‐α, IL‐6; ↑IL‐10), oxidative stress (↓TOC, ↑TAC) and apoptosis (↓Bax/Bcl‐2, ↓Caspase‐3/9, ↓cyt c) in an acetic acid‐induced colitis model." (PMID 40688608, 2025). "As expected, induction of colitis with DSS triggered a strong pro-inflammatory response, evidenced by significant upregulation of TNF-α, IL-6, and IL-17 expression." (PMID 40869289, 2025).
colitis (continued). "The UC group showed severe colitis, increased TNF‐α and IL‐6, decreased IL‐10, elevated TOC, reduced TAC, altered VEGF/EGF mRNA, PI3K/AKT activation, and increased apoptosis (Bax/Bcl‐2 ratio, Cytochrome c, Caspase‐9, Caspase‐3)." (PMID 40688608, 2025). "The expression of colitis‐related genes, including COX‐2, TNF‐α, IL‐6, and IL‐10, was detected in the colon using RT‐qPCR." (PMID 39803293, 2025). "In models of dextran sulfate sodium (DSS)-induced colitis, Akkermansia muciniphila (AKK) demonstrated protective effects by decreasing inflammatory cytokines (TNF-α, IL-1β, IL-6) and inhibiting NLRP3 inflammasome activation." (PMID 40299512, 2025). "The pretreatment with A. muciniphila alleviated the phenotype of DSS-induced colitis mice through activating NLRP3 and decreasing the expression of pro-inflammatory cytokines (IL1β, IL-6) and chemokines MCP-1." (PMID 41488633, 2025). "A recent study demonstrated that Amuc_2109 reduces the levels of TNF-α, IL-1β, and IL-6, as well as NLRP3 expression, while enhancing intestinal barrier function and improving DSS-induced colitis." (PMID 40028328, 2025). "TTM significantly reduced colonic inflammation and the levels of IL-6, IL-1β, and TNF-α in colitis mice." (PMID 40969742, 2025). "Like I3C, DIM attenuated the DSS-induced colitis by inhibiting TNF-α, IL-6, IFN-γ, IL-10, iNOS, COX-2, NO, PGE2, myeloperoxidase activity (MPO), and NF-kB." (PMID 40094833, 2025). "The pre-treatment of A. muciniphila to colitis mice not only stabilized the colon mucosal barrier, regulated inflammatory cytokines (e.g., TNF-α, IL-6) and chemokines MIP-1, but also alleviated dysbiosis of the gut microbiome." (PMID 41488633, 2025). "Deletion of EGFR in macrophages in DSS-colitis mice leads to the increase of anti-inflammatory cytokines, such as IL-10 that inhibits the release of proinflammatory cytokines such as IL-6, IL-8 and TNF, limiting colitis development." (PMID 39966897, 2025). "When curcumin-encapsulated grapefruit exosomes are administered to DSS-induced colitis-affected mice, colon tissue extracts showed lower levels of TNF-α, IL6, and IL-1β in comparison to other groups, according to ELISA analysis." (PMID 40490812, 2025). "The administration of L. paracasei strains (KBL382, 384, 385) demonstrated protective effects in DSS-induced colitis models, with L. paracasei KBL382-treated mice showing reduced levels of pro-inflammatory cytokines, including IL-4, IL-6, TNF-α, and IL-17a." (PMID 40243712, 2025). "Similar intervention outcomes were observed in patients with colitis, with EEN reducing serum IL-6, interleukin 1 (IL-1), and TNF-α levels and attenuating the state of intestinal oxidative stress." (PMID 41393952, 2025). "For example, studies have shown that the transplantation of M2 macrophages can reduce the production of pro-inflammatory cytokines (e.g., IL-6 and TNF-α) in animal models of acute kidney injury and colitis." (PMID 41143725, 2025). "For example, administering B. longum expressing a PEP-1-hMnSOD fusion protein in DSS-induced colitis mice reduced inflammatory cytokines (TNF-α, IL-1β, IL-6, and IL-8) and mitigated histological damage in colonic tissues." (PMID 40243712, 2025). "In the DSS-induced colitis mouse model, we observed that P. scabiosaefolia effectively suppressed the secretion of TNF-α and IL-6 and downregulated their mRNA transcription levels." (PMID 40238255, 2025). "Macrophage TIM3 can inhibit the expression of proinflammatory cytokines such as TNFα, IL-1β, IL-6, IL-12, and NOS2 in dextran sodium sulfate (DSS)-induced colitis." (PMID 41307843, 2025). "In colitis mice, the CCFM1426 and VA combination significantly reduced IL-6 and TNF-α levels whilst increasing IL-10 levels (p < 0.05)." (PMID 40777179, 2025). "Specifically, the abundance of Bacteroides and Escherichia-Shigella as opportunistic pathogens was significantly positively correlated with key pathological markers of colitis such as MPO, MDA, TNF-α, IL-6, and IL-1β." (PMID 41010513, 2025).